P2RY4 (pyrimidinergic receptor P2Y4)
Description:
Receptor for UTP and UDP coupled to G proteins that activate a phosphatidylinositol-calcium second messenger system. Not activated by ATP or ADP.
Synonyms: P2Y4; UNR; NRU; P2P
Tractability: Small molecule: a drug acting on it is in phase 2 or 3 trials; a high-quality ligand is known; it belongs to a druggable protein family. Antibody: its Gene Ontology location is reachable by antibodies, with high confidence; UniProt places it where antibodies can reach, with medium confidence; UniProt predicts a signal peptide or a membrane-spanning region. PROTAC: a small molecule that binds it is known.
Target class: Purine receptor; Small molecule receptor (family A GPCR); Membrane receptor; Family A G protein-coupled receptor; Nucleotide-like receptor (family A GPCR)
Gene: Protein-coding gene on chromosome X (70,258,166 to 70,260,204, reverse strand). Ensembl gene ENSG00000186912.
Subcellular location: Cell membrane
Pathways (Reactome):
Signal Transduction: G alpha (i) signalling events; P2Y receptors
Gene Ontology:
Molecular function: protein binding; G protein-coupled UTP receptor activity; G protein-coupled purinergic nucleotide receptor activity; G protein-coupled receptor activity
Biological process: cellular response to ATP; G protein-coupled receptor signaling pathway; phospholipase C-activating G protein-coupled receptor signaling pathway; positive regulation of cytosolic calcium ion concentration; G protein-coupled purinergic nucleotide receptor signaling pathway; transepithelial chloride transport
Cellular component: plasma membrane; membrane
Homologues: Orthologues: chimpanzee P2RY4 (99% identical), macaque P2RY4 (97% identical), rabbit P2RY4 (89% identical), pig P2RY4 (88% identical), rat P2ry4 (83% identical), mouse P2ry4 (81% identical), tropical clawed frog p2ry4 (51% identical). Paralogues in human: P2RY2 (52% identical), P2RY1 (36% identical), P2RY6 (35% identical), OXGR1 (28% identical), SUCNR1 (25% identical), HCAR3 (23% identical), HCAR2 (22% identical), FFAR2 (20% identical), HCAR1 (20% identical), OXER1 (20% identical), GPR31 (19% identical), GPR42 (19% identical), and 3 more.
Diseases named in the same sentence as P2RY4 in open-access papers:
P2RY4 is named in the same sentence as 29 diseases in open-access papers, as found by Europe PMC text mining. Sharing a sentence is not in itself a finding about the gene and the disease. The quoted sentences say what the papers report.
status epilepticus (3 papers, 2018 to 2019). Status epilepticus is defined as a continuous seizure lasting more than 30 min, or two or more seizures without full recovery of consciousness between any of them. "Status epilepticus: Increased P2ry2, P2ry4, and P2ry6 and decreased P2ry1, P2ry12, P2ry13, and P2ry14 transcript levels; increased P2Y1, P2Y2, P2Y4, and P2Y6 and decreased P2Y12 protein levels." (PMID 29563872, 2018). "Both, intraamygdala KA and intraperitoneal pilocarpine-induced status epilepticus increased the transcription of the uridine-sensitive P2Y receptors P2ry2, P2ry4, and P2ry6 in the hippocampus." (PMID 29563872, 2018).
liver cancer (2 papers, 2019 to 2025). An epithelial or non-epithelial malignant neoplasm that arises from the liver. "However, few studies have investigated the relationships among P2RY4, GPR68, and liver cancer, and elucidating these relationships could be a direction for future research." (PMID 31236404, 2019).
lung carcinoma (1 paper, 2020). "Next, we determined the expression levels of P2X sub-families P2RX1–7 and P2Y receptors P2RY1, P2RY2, P2RY4, P2RY5 (LPAR6), P2RY6, P2RY7 (LTB4R), P2RY8, P2RY9 (LPAR4), P2RY10–14 in normal lung tissues and lung cancer tissues." (PMID 32638267, 2020).
tumor (4 papers, 2013 to 2024). "Quantification of the other subtypes confirmed that P2RY2, P2RY4 and P2RY14 were not significantly upregulated in the tumor samples compared to normal samples." (PMID 38773214, 2024).
P2RY4 also shares sentences with these, for which no sentence is quoted: myocardial infarction (4 papers); astrocytoma (2); cancer (2); acute kidney injury (1); Alzheimer disease (1); amyotrophic lateral sclerosis (1); atherosclerosis (1); bronchospasm (1); colon cancers (1); coronary artery atherosclerosis (1); cystic fibrosis (1); dry eye (1); Focal cortical dysplasia (1); heart (1); Hypertension (1); infarction (1); infection (1); Infertility (1); Insulin resistance (1); kidney damage (1); kidney injury (1); multiple sclerosis (1); Parkinson disease (1); Sepsis (1); type 2 diabetes (1).